TNF (tumor necrosis factor)
Diseases named in the same sentence as TNF in open-access papers (continued):
Sharing a sentence is not in itself a finding about the gene and the disease.
ulcerative colitis (continued). "Intestinal inflammation intensity in the ulcerative colitis is positively correlated with TLR8 and inflammatory cytokines such as IL-6 and TNF-α." (PMID 30044791, 2018). "We found that the patients suffered ulcerative colitis had high serum SDC1 levels,presented with increased levels of P65, tumour necrosis factor alpha (TNF‐α) and IL‐1β and higher circulating neutrophils." (PMID 27558380, 2017). "Golimumab is a fully humanized monoclonal antibody against TNF-α and is the latest anti-TNF agent to receive FDA approval for treatment of moderate-to-severe ulcerative colitis." (PMID 25344680, 2015). "Here, we test whether IL-10 can favour the response to glucocorticoids by improving the TNFα-induced intestinal barrier damage (assessed by transepithelial electrical resistance) in Caco-2 monolayers, and their possible implications on glucocorticoid responsiveness in active ulcerative colitis." (PMID 26090671, 2015). "Specifically, increased levels of TNF-α, IL-1β, IFN-γ, IL-6, and IL-8 have been reported in ulcerative colitis patients." (PMID 23630633, 2013). "L. plantarum K68 (K68), a probiotic strain isolated from fu-tsai, has been shown to reduce the production of pro-inflammatory cytokines (TNF-α, IL-β, and IL-6) in dextran sulfate sodium (DSS)-induced ulcerative colitis BALB/c mice." (PMID 23690866, 2013). "Recently, we reported that production of pro-inflammatory cytokines, IL-1β, IL-6, and TNF-α, was significantly decreased by oral administration of L. plantarum K68 in DSS-induced ulcerative colitis mice." (PMID 23690866, 2013). "At sites of intestinal inflammation, granulocytes and macrophages produce high levels of pro-inflammatory cytokines, including interleukin (IL)-1β, IL-6, and tumor necrosis factor (TNF)-α, which are directly involved in the pathogenesis of ulcerative colitis." (PMID 22479648, 2012). "In patients undergoing restorative proctocolectomy for medically refractory ulcerative colitis, a three-stage SPLS procedure was advocated when patients received more than 20 mg of prednisolone or anti-TNF-α agents such as infliximab or adalimumab." (PMID 22619710, 2012). "Approximately 50% of the patients with ulcerative colitis (UC) are primarily nonresponsive to anti‐tumor necrosis factor (TNF) therapy or lose their responsiveness over time." (PMID 39739648, 2025). "In addition, 12-week treatment with S. boulardii improved azoxymethane and DSS-induced ulcerative colitis (UC) carcinogenesis in C57BL/6J mice, which was attributed to a decrease in colon TNFα and IL-6 levels." (PMID 40872558, 2025). "That disease activity correlated with circulating concentrations of IL17, IL10, IL8, IL6 and interferon‐γ when assessed in cross‐sections of patients with ulcerative colitis is not new, as was the poor correlation with levels of TNFα." (PMID 40584280, 2025). "5-ASA: 5-Aminosalicylic Acid, Anti-TNF: Anti-Tumour Necrosis Factor, IV: Intravenous, JAK inhibitors: Janus Kinase Inhibitors, RCT: Randomized Controlled Trial, SC: Subcutaneous, UC: Ulcerative Colitis, UNIFI: Ustekinumab as Induction and Maintenance Therapy for Ulcerative Colitis, UST: Ustekinumab." (PMID 40896002, 2025). "Decreased plasma levels of hs-CRP, TNF-α, plasma DA0, ET, D-lactic acid, IL-8, and IL-6 and increased CD4/CD8 ratio and CD4+ levels, enhancing the remedying impact in ulcerative colitis patients and regulating T cell frequency, in addition to reducing plasma inflammatory factors." (PMID 38398870, 2024). "In patients with ulcerative colitis (UC), the development of an antidrug antibody (ADA) to anti-tumor necrosis factor (TNF)α agent is a crucial problem which aggravates the clinical course of the disease, being cited as one of the most common causes for discontinuing anti-TNFα treatment." (PMID 38672155, 2024).
ulcerative colitis (continued). "While Th1 and Th17 cells are involved in IBD-associated inflammation, with the secretion of cytokines, such as TNF-α, IFN-γ, and IL-6 by Th1, and IL-17, IL-22, and IL-21 by Th17, Th2 cells contribute to intestinal mucosa inflammation in ulcerative colitis (UC) by secreting IL-4." (PMID 38892375, 2024). "Retrospective studies have shown promise in patients with CD or ulcerative colitis (UC) receiving combination therapy involving anti‐TNF and UST, resulting in clinical responses without adverse reactions." (PMID 38533646, 2024). "Zhao Tian-yu reported that a Phellinus igniarius polysaccharide (A3) with an α-1, 6-D-GALp structure could significantly reduce IL-6, IL-1β, and TNF-α mRNA expression in RAW264.7 cells and mice with LPS-induced ulcerative colitis." (PMID 39202931, 2024). "Anti-tumor necrosis factor (TNF) -α antibodies, including infliximab (IFX), adalimumab (ADA), and golimumab, which were the first biologic therapeutic agents, have a crucial position in advanced therapy for ulcerative colitis (UC)." (PMID 38166010, 2024). "Oral administration of C. bovis was also found to alleviate the inflammatory damage in the colon tissue of mice ulcerative colitis model induced by dextran sulfate sodium, accompanied by reduced levels of myeloperoxidase, SOD, and mRNA expression of IL-1β, IL-6, and TNF-α." (PMID 36903252, 2023). "In the present study, we treated the colonoids with TNF and the TLR3 ligand Poly(I:C), and analyzed the conditioned medium for chemokines and NGAL, which is expressed in IECs during active Crohn’s colitis, ulcerative colitis, and collagenous colitis." (PMID 36793710, 2023). "Serum IL-6, IL-8, and TNF-α levels were significantly higher in SIBO positive ulcerative colitis patients as compared to SIBO negative patients." (PMID 35630404, 2022). "Moreover, it inhibited TNF-α, IL-1β, IL-12 IL-17A, and interferon-γ (IFN-γ) contents that were elevated due to ulcerative colitis." (PMID 36079895, 2022). "The present study found that APH reduced the inflammatory response by upregulating the content of IL-10 and downregulating the content of TNF-α, IL-1β, and IL-6, which demonstrates that APH could alleviate ulcerative colitis." (PMID 36359970, 2022). "In addition, the interplay between inflammation and the NOTCH signaling has been amply reviewed and it has been reported that NOTCH1 and HES1 in co-operation with TNF-α can suppress PPAR-γ to play a crucial role in the pathogenesis of ulcerative colitis." (PMID 36386153, 2022). "Studies have shown that neutrophils from patients with ulcerative colitis can produce NETs upon stimulation with TNF-α, and reduced NET formation and their related proteins can be observed in patients successfully treated with anti-TNF-α therapy." (PMID 36532016, 2022). "It was recently shown that cyclooxygenase-2 (COX-2), the rate-limiting enzyme in the arachidonic acid signaling pathway, was constitutively overexpressed in ulcerative colitis patients who did not respond to TNFα inhibitors." (PMID 33776573, 2021). "In DSS-induced ulcerative colitis, it is well known that the expression of iNOS and COX-2 is upregulated, followed by the increased expression of pro-inflammatory cytokines such as IL-6 and TNF-α." (PMID 31569788, 2019). "Combined therapy with tacrolimus (TAC) and an anti‐tumor necrosis factorα (TNFα) antibody is used to induce remission in ulcerative colitis (UC) patients who have not responded to monotherapy with either drug." (PMID 31832554, 2019). "More importantly, in patients with IBD, tumor necrosis factor-α (TNF-α) is overexpressed in the monocytes and macrophages that infiltrate the mucosa; there are, however, substantial differences between CD and ulcerative colitis in the level and localization of monocyte infiltration." (PMID 29862296, 2018).
ulcerative colitis (continued). "The key role of cytokines such as TNF-α, IL-6, IL-1 β and leukotriens in the pathogenesis of IBD, particularly ulcerative colitis suggests that coriander may act through decreasing the synthesis or function of cytokines." (PMID 27222834, 2016). "Moreover, we will discuss efficacy and safety data of golimumab (a new subcutaneous anti-tumor necrosis factor (TNF) antibody), Avaxia (an orally delivered anti-TNF antibody), and Budesonide MMX; all have been developed for the treatment of ulcerative colitis." (PMID 26031830, 2015). "In addition, the activity of proinflammatory cytokines such as tumor necrosis factor α (TNF-α), interleukin 1β (IL-1β), and IL-6 is increased in the colonic mucosa of patients with ulcerative colitis." (PMID 24971344, 2014). "Third, only a limited set of immune markers (CD4, CD8, and IL-6) was analyzed; inclusion of additional cytokines and functional markers (e.g.,TNF-α, TGF-β, FOXP3, IL-17, granzyme B) could provide a more comprehensive understanding of immune regulation in ulcerative colitis." (PMID 41465205, 2025). "For instance, ginger-derived exosomes loaded with TNF-α siRNA and ZIF-8 nanocarriers have demonstrated significant immunomodulatory effects by targeting and silencing TNF-α genes, suppressing inflammation, and modulating the gut microbiota to reduce inflammation in ulcerative colitis." (PMID 40438295, 2025). "Inflammatory cytokines play crucial roles in the development of ulcerative colitis, as shown in DSS-treated mice, which presented significantly increased levels of inflammatory cytokines, including IL-1β, IL-23, and IL-17F, in colon extracts, whereas TNF-α levels were elevated in the serum." (PMID 40576745, 2025). "One study reported the use of mucosal proinflammatory gene signatures (TNF, interleukin 1 alpha [IL1A], regenerating family member 1 alpha [REG1A], IL8, interleukin 1 beta [IL1B], and leukocyte immunoglobulin-like receptors A [LILRA]) in patients with ulcerative colitis." (PMID 39483464, 2024). "Patients with ulcerative colitis only had higher levels of erythrocyte sedimentation rate (p = 0.000), CRP (p = 0.000), triglyceride (p = 0.000), Ag PLT ADP (p = 0.000), leukocyte (p = 0.001), fecal calprotectin (p = 0.000), IL-6 (p = 0.000), and TNF-α values (p = 0.000) than healthy controls." (PMID 36984554, 2023). "Interestingly, it was found that COX-2 is overexpressed in RA and ulcerative colitis patients and is constitutively overexpressed in TNFα inhibitor nonresponders." (PMID 33776573, 2021). "Inhibition of tumor necrosis factor-α (TNF) signaling is beneficial in the management of ulcerative colitis (UC), but up to one-third of patients do not have a clinical response of relevance to TNF inhibitors during induction therapy (i.e. primary non-responders [PNRs])." (PMID 30190207, 2018). "Moreover, black raspberries induced anti-inflammatory activity by suppressing tissue levels of COX-2 as well as proinflammatory cytokine tumor necrosis factor-alpha (TNF-α), prostaglandin E2 (PGE2) and IL-1β in DSS-induced ulcerative colitis in male C57BL/6J mice." (PMID 26840292, 2016). "Induction of MMP-1 by IL-1β or TNF was completely abolished by imipramine in all the investigated primary fibroblasts, including three different sets from healthy control (CO I, CO II, CO III) and three sets from patients with ulcerative colitis (UC I, UC II, UC III)." (PMID 19787068, 2009). "It was suggested that olsalazine has a therapeutic effect on ulcerative colitis induced by DSS in mice, and the mechanism may be related to the increase of IL-2, IL-10, IL-22, TGF, and EGF and the decrease of the expression of IL-7, IL-17, TNF-α, IL-1β, and IFN-γ." (PMID 37610966, 2023). "Further work is required to determine if these findings are found in other non-western populations, and indeed in other populations of patients with IBD such as those with ulcerative colitis and in non-IBD patients treated with an anti-TNF." (PMID 37551994, 2024).
ulcerative colitis (continued). "In the present study, we applied colonoids derived from non-IBD controls and ulcerative colitis patients to identify induction and effects of IBD-drugs on antigen presentation in IECs in the context of Tumor Necrosis Factor (TNF)-driven inflammation." (PMID 35655783, 2022). "So, in selected patients with moderate to severe active ulcerative colitis who have failed to respond or are poorly responsive to standard pharmacologic forms of treatment with corticosteroids and immunosuppressive agents, therapy with an anti-TNF-α agent may be considered." (PMID 24475168, 2014). "Conversely, TRUC mice develop spontaneous juvenile ulcerative colitis resulting from a pro-inflammatory response to the commensal microbiota (germ-free TRUC mice do not develop the disease) driven by dendritic cells and TNFα." (PMID 34884737, 2021).
Cognitive impairment (641 papers, 2008 to 2026). Abnormal cognition is characterized by deficits in thinking, reasoning, or remembering. "Upon administration, LPS activates microglia and astrocytes, which trigger pro-inflammatory modulators (IL-1β, IL-6, and TNF-α), causing the progression of neurological complications such as cognitive impairment." (PMID 41557677, 2026). "In 2VO rats, BOHXTN (2.5–10 g/kg, 30 days) alleviated cognitive impairment, neuron loss, decreased inflammation by inhibiting IL-1β, TNF-α, cleaved caspase-3, and iNOS by activating the PI3K/AKT and LXRα/CYP7A1 signaling pathways." (PMID 41230091, 2025). "Chronic inflammation serves as a central pathogenic driver in cerebrovascular and cognitive disorders, orchestrated by pro-inflammatory cytokines including interleukin-6 (IL-6), tumor necrosis factor-α (TNF-α), and interleukin-1β (IL-1β)." (PMID 40918522, 2025). "High levels of IL-6 and TNF-α are linked to mood and cognitive abnormalities, while abnormal cytokine signaling in schizophrenia is linked to poor brain connections and developmental alterations." (PMID 39861166, 2025). "Increased TNF-α has also been shown to be associated with lower hippocampal volume and cognitive impairment." (PMID 40016149, 2025). "TNF-α, a key cytokine in neuroinflammation, impairs synaptic plasticity, causing cognitive deficits and memory impairments in neurodegenerative and psychiatric illnesses." (PMID 39861166, 2025). "Elevated TNF-α levels are associated with a significantly higher risk of cognitive impairments, highlighting the potential significance of this biomarker as an inflammatory marker affecting neuropsychological health in the study group." (PMID 40137151, 2025). "Infliximab is a TNF inhibitor that acts on a pro-inflammatory cytokine found to be elevated in individuals with BD and potentially linked to cognitive impairments observed in this clinical population." (PMID 40430486, 2025). "In summary, this study demonstrates that CP induces cognitive deficits associated with increased hippocampal levels of inflammatory markers (IL-1β, IL-6, NF-κB, and TNF-α) and apoptotic markers (caspase-3 and BAX)." (PMID 41256255, 2025). "It has been shown that ketamine inhibits pro-inflammatory cytokines such as interleukin-6 (IL-6) and tumor necrosis factor-alpha (TNF-α), which have been linked with cognitive impairment." (PMID 40809865, 2025). "This is consistent with our findings, which show that elevated TNF-α levels are associated with a higher risk of cognitive impairments, potentially reflecting inflammatory processes in the central nervous system." (PMID 40137151, 2025). "Patients with steatohepatitis often show mild cognitive impairment prior to the onset of cirrhosis and show neuroinflammation and neuronal loss in the hippocampus, along with increased IL‐1β and TNF‐α." (PMID 41141377, 2025). "Elevated levels of TNF-α in the AD brain are linked to neuronal apoptosis and synaptic loss, both of which are central to the cognitive deficits seen in AD." (PMID 41009474, 2025). "Peripheral inflammation elevates brain pro-inflammatory cytokines (e.g., IL-1β, TNF-α), exacerbating neuroinflammation-associated cognitive deficits in encephalopathy patients." (PMID 41291751, 2025). "Among inflammatory markers, interleukin-6 (IL-6) and tumour necrosis factor-alpha (TNF-α) have been linked to both psychosis pathophysiology and related cognitive impairments." (PMID 40637145, 2025). "Inflammatory cytokines IL-1β and TNFα have been shown to be increased in AD models and around Aβ deposits and increased in patients at risk for conversion from mild cognitive impairment to AD." (PMID 38543105, 2024). "Cytokines, including TNF, IL-1 ß, and IL-6, have been described to affect the synaptic plasticity and neurogenesis which are implicated in learning and cognitive impairment." (PMID 38150137, 2024).